AQP5 (aquaporin 5)
Diseases named in the same sentence as AQP5 in open-access papers (continued):
Sharing a sentence is not in itself a finding about the gene and the disease.
ovarian carcinoma (16 papers, 2012 to 2024). A malignant neoplasm originating from the surface ovarian epithelium. "AQP5 expression level was also associated with the sensitivity of ovarian cancer cells to chemotherapy." (PMID 32679804, 2020). "As with AQP9, high AQP5 expression was characteristic of malignant ovarian tumors associated with lymph node metastases." (PMID 33271827, 2020). "Our results showed that AQP5 mRNA expression was significantly associated with better OS in all ovarian cancer patients and well differentiated ovarian cancer patients." (PMID 29472315, 2018). "The higher expression of AQP5 mRNA level was associated with better OS in all ovarian cancer patients, HR = 0.84 (0.73–0.97), P=0.015." (PMID 29472315, 2018). "Overexpression of AQP5 have been reported to be associated with many kinds of cancers such as colorectal, cervical, lung, breast and epithelial ovarian cancer, and to be a potential prognostic biomarkers." (PMID 25298246, 2014). "Similarly, epigallocatechin gallate treatment decreases AQP5 mRNA concentrations causing a decrease in proliferation of SKOV3 ovarian cancer cells." (PMID 25344048, 2014). "It suggested that AQP5 was positively associated with both proliferation and migration of ovarian cancer cells, which may also have affected the growth of tumor in the xenoplantation model." (PMID 25298246, 2014). "Inhibiting AQP5 reduced the migration and proliferation of 3AO ovarian carcinoma cells along with the rates of tumour development, suggesting that AQP5 is engaged in the genesis and dissemination of tumours." (PMID 38336645, 2024). "AQP5 knockdown impaired growth and migration of epithelial ovarian cancer cells and sensitivity to chemotherapy." (PMID 33499000, 2021). "Whereas AQP1 (stages I + II and III + IV), AQP4 (stages I + II and III + IV), and AQP5 (stage I + II) expressions revealed remarkably unfavorable OS in all ovarian cancer patients." (PMID 29472315, 2018). "Down-regulating AQP5 inhibited proliferation and migration of cultured human epithelial ovarian cancer 3AO Cell." (PMID 25298246, 2014). "Our studies also suggested the probable relationship between NF-kappaB pathway and AQP5 expression in human ovarian cancer cells." (PMID 25298246, 2014). "Our previous studies also demonstrated that AQP5 was highly expressed in epithelial ovarian cancer and contributed to the progress of ovarian cancer." (PMID 25298246, 2014). "In contrast to our findings, AQP5 mRNA expression levels were found to be elevated in malignant ovarian tumors in women and such an increase was positively correlated to the ascites volume." (PMID 25344048, 2014). "Yang and colleagues demonstrated that AQP5 protein had a significant relationship with cell proliferation rate, and also that cisplatin may elicit a concentration-dependent reduction in AQP5 activity in human ovarian cancer CAOV3 cells." (PMID 38336645, 2024). "According to numerous research, AQP5 expression levels are directly correlated with tumour stage, lymph node metastases, and poor diagnosis, suggesting that AQP5 may be used as a potential biomarker for ovarian cancer." (PMID 38336645, 2024). "Epigallocatechin gallate suppressed ovarian cancer SKOV3 cell growth and induced apoptosis in a time and dose dependent manner by suppressing AQP5, which could be associated with nuclear transcription factor, nuclear factor kappa B (NF-kB)." (PMID 38336645, 2024). "AQP5 levels in ovarian cancer similarly have been correlated with tumor growth, as well as lymph node metastasis and volume of malignant ascites, suggesting AQP5 could be a prognostic factor." (PMID 33499000, 2021). "Multiple studies have reported direct correlations of AQP5 expression levels with tumor grade, lymph node metastasis and poor prognoses, suggesting AQP5 could be a prognostic factor for ovarian cancer." (PMID 32679804, 2020).
ovarian carcinoma (continued). "Besides, the high abnormal expression of aquaporin 5 (AQP5) is associated with tumorigenesis and the development of ovarian cancer by regulating the NF-κB pathway." (PMID 33113766, 2020). "A change in AQP5 expression was also noted in the ovarian cancer cell line CAOV3 and SKOV3." (PMID 33271827, 2020). "There are also many related studies in ovarian cancer, and the expression of AQP5 in ovarian cancer is significantly increased, which is consistent with our previous gene expression correlation analysis using samples from the UCSC database, and is associated with the formation of ascites." (PMID 33343628, 2020). "Taken together, our results indicated that high level of AQP3 and AQP5 might favor clinical outcomes in ovarian cancer." (PMID 29472315, 2018). "Since greater AQP5 expression has been positively correlated with ascites volume and lymph node metastasis in human subjects with ovarian tumor, we sought to elucidate the expression of AQP5 in the chicken model of ovarian tumor and in ascites-derived chicken ovarian cancer (COVCAR) cell lines." (PMID 25344048, 2014). "All of these data suggested that AQP5 was involved in the migration of ovarian cancer cells." (PMID 25298246, 2014). "To investigate the role of AQP5 in ovarian tumorigenesis, we firstly examined whether AQP5 involved in the proliferation of ovarian cancer cells." (PMID 25298246, 2014). "However, treatment of CAOV3 ovarian cancer cell line with cisplatin decreases AQP5 protein expression and growth rate." (PMID 25344048, 2014). "All of these preliminary findings explored the role AQP5 in ovarian cancer and indicated that AQP5 is a putative oncogene and may play multi roles in ovarian carcinoma." (PMID 25298246, 2014). "Therefore, in this study, we used lentivirus mediated RNA interference method to down-regulate the expression to investigate the possible function of AQP5 in epithelial ovarian cancer cells." (PMID 25298246, 2014). "Notably, it was reported recently that epigallocatechin gallate, a potential anticancer drug, inhibited the proliferation and induced the apoptosis of ovarian cancer SKOV3 cells through the downregulation of AQP5 expression." (PMID 23148732, 2012). "However, the correlation with prognosis depends on the histological type of ovarian carcinoma; specifically, high AQP5 expression is related to poorer prognosis in serous carcinoma, while low AQP1 expression was evident in clear cell carcinomas with poorer prognosis." (PMID 33807998, 2021). "In addition, the downregulation of AQP5 expression can inhibit ovarian cancer development." (PMID 33343628, 2020). "High hazard ratios were noted for AQP5 and AQP9 in glioma and ovarian cancers; more research is needed on their possible pathophysiological roles." (PMID 32679804, 2020). "In malignant forms of ovarian cancer, a much higher expression of AQP1, AQP5, AQP9 was observed compared to benign forms of ovarian cancer or normal ovaries." (PMID 33271827, 2020). "Our results revealed that higher AQP0, AQP1, and AQP4 mRNA expression were correlated with poor OS, whereas higher AQP3, AQP5, AQP6, AQP8, AQP10, and AQP11 showed better OS in ovarian cancer patients." (PMID 29472315, 2018). "Subsequent expression of AQP0, AQP5, and AQP10 mRNA expression had better OS in grade I ovarian cancer patients." (PMID 29472315, 2018). "However, the study about the prognostic role of AQP5 in ovarian cancer has not been studied yet." (PMID 29472315, 2018).
diabetes (13 papers, 2017 to 2023). "In conclusion, polydatin has a potent protective effect on diabetes-related salivary gland hypofunction through its antioxidant and anti-glycation activities, and its AQP5 upregulation." (PMID 35056946, 2021). "AQP5 overexpression and polydatin’s antioxidant and anti-glycation actions boosted mucin accumulation, and they found that polydatin had a significant protective impact on diabetes-related salivary gland hypofunction." (PMID 35735612, 2022). "In diabetes condition, the salivary flow rate, amylase activity, and aquaporin-5 and Na+/H+ exchanger (NHE-1) expressions were markedly decreased, whereas they were more significantly recovered in the sequential treatment of IXD-lactobacillus extract than in each single treatment." (PMID 32392818, 2020). "Therefore, significant decrease in AQP5 in the submandibular glands of the present study indicates the degenerative effect of maternal diabetes on the morphological differentiation and the secretory function of the glands." (PMID 30304036, 2018). "Other studies have analyzed the urine levels of AQP5 and AQP2 excreted by exosomes in 35 patients with diabetes, suggesting that exosomal AQP5 and AQP2 may be used as novel noninvasive biomarkers to help classify the clinical stages of DN." (PMID 35395948, 2022). "In this work, we analyzed the urine excretion of AQP5 and AQP2 (uAQP5 and uAQP2), via exosomes, in 35 diabetic patients: 12 normoalbuminuric with normal renal function (DM), 11 with proteinuric nondiabetic nephropathy (NDN), and 12 with histological diagnosis and classification of DN." (PMID 28246612, 2017). "In diabetes, high glucose concentration impaired or not AQP5 distribution and expression." (PMID 37681902, 2023).
asthma (12 papers, 2006 to 2025). "In a recent study, increases in AQP1 and AQP5 content in the sputum were proposed as possible diagnostic markers for mild asthma." (PMID 30397774, 2019). "Previous studies also showed that AQP1 and AQP5 levels were significantly reduced in OVA‐induced mouse asthma models, which induced increased alveolar fluid viscosity and mucus plug formation." (PMID 41280738, 2025). "This substantiates the implication of AQP5 in the progression of chronic inflammation and mucus hyperplasia in the context of asthma." (PMID 39440058, 2024). "In the study, house dust mite (HDM)-induced asthma mice displayed features of airway inflammation, Th2 cell aggregation, and mucin hypersecretion comparable to those observed in AQP5 gene knockout mice." (PMID 39440058, 2024). "Interleukin-13 (IL-13), a central regulator of Th2-dominated respiratory disorders such as asthma, abolished the increase in Aqp5 mRNA level during airway epithelial cell differentiation." (PMID 36768212, 2023). "AQP-1 plays a role in fluid flux and eosinophil movement, whereas AQP-5 is involved in pulmonary hyper-responsiveness and airway inflammation in asthma." (PMID 38203236, 2023). "A new study has also shown that the polysaccharide in aqueous decoction of Pinelliae Rhizoma can reduce the expression of AQP5 mRNA in colon tissue of rats in an asthma model, thus interfering with the asthma process." (PMID 36532729, 2022). "In addition, reduced Aqp5 mRNA and AQP5 protein levels were detected in lungs from an interleukin-13-induced mouse model of asthma." (PMID 36768212, 2023). "Two genes, anp and aqp5 may play a role in asthma and edema, respectively." (PMID 16533406, 2006). "Upon analyzing sputum samples from 34 patients with mild to moderate asthma, a positive correlation was observed between AQP1 and AQP5 levels." (PMID 39440058, 2024). "Hence, our hypothesis posits that both AQP1 and AQP5 could serve as potential markers for asthma." (PMID 39440058, 2024). "Asthma models based on ovalbumin instillation exhibit changes in expression levels of AQP1, AQP3, AQP4, and AQP5." (PMID 30397774, 2019). "Another study on ovalbumin-induced asthma models also reported reduced mRNA levels for AQP1, AQP4, and AQP5 but elevated AQP3 mRNA levels." (PMID 30397774, 2019). "Recently, a mouse model of asthma induced by ovalbumin has been used to study the mRNA and protein expression of AQP1 and AQP5." (PMID 24917931, 2014). "The authors found that both AQPs were significantly increased by treatment with dexamethasone, ambroxol, and terbutaline, indicating that AQP1 and AQP5 are closely related to pulmonary edema but not to eosinophil infiltration or mucus secretion in patients with asthma." (PMID 24917931, 2014). "A similar negative correlation between AQP5 and MUC5AC was also found in the lung tissue of the asthma model of mouse; the MUC5AC expression was significantly increased when AQP5 expression was downregulated by RNA interference." (PMID 28630635, 2017).
lymph node metastasis (12 papers, 2011 to 2025). "The second is that AQP5 expression is associated with cancer stage, pathology differentiation, and lymph node metastasis." (PMID 28229027, 2017). "AQP5 expression was also associated with lymph node metastasis (P = 0.001)." (PMID 25217331, 2014). "AQP5, as a water channel protein, is also a predictor of early tumor recurrence, lymph node metastasis, and poor clinical outcome in cancer patients." (PMID 25217331, 2014). "The AQP5 over-expression was also associated with TNM stage (P = 0.042), and lymph node metastasis (P = 0.001)." (PMID 25217331, 2014). "Increased expression levels were correlative to TNM stage (classification of malignant tumors), lymph node metastasis, and distant metastasis indicating that AQP5 expression level may serve as prognostic marker." (PMID 30555637, 2018). "Furthermore, AQP5 also plays a key role in cervical cancer; its high expression is positively correlated with the expression of Ki-67, and both are significantly correlated with lymph node metastasis and poor prognosis." (PMID 33343628, 2020). "The AQP5 protein is up-regulated in prostate cancer and is closely related to advanced ABCD stage, lymph node metastasis, CTCs and poor prognosis." (PMID 25217331, 2014). "Other studies have revealed that silencing AQP5 expression can promote apoptosis of colorectal tumor cells, and AQP5 expression is related to not only higher TNM stage, lymph node metastasis and distant metastasis, but also the number of peripheral blood circulating tumor cells (CTC) of patients." (PMID 40760228, 2025). "AQP5 in tissues with lymph node metastasis showed higher levels of expression than tissues without lymph node metastasis." (PMID 30555637, 2018). "Tumor grade and semi-quantitative measurement of AQP5 labeling intensity and proportion in the invasive ductal carcinoma with or without lymph node metastasis." (PMID 22145049, 2011).
pancreatic cancer (11 papers, 2015 to 2025). "We also found that CpG islands of AQP5 methylation were associated with unfavorable prognosis, suggesting that the AQP5 methylation level could be used as a prognostic marker of pancreatic cancer." (PMID 35619903, 2022). "Similarly, GGT1 is implicated in pancreatic cancer by genome-wide association studies while AQP5 and CABLES1 enhance tumour progression." (PMID 25944692, 2015). "In particular, AQP1, AQP3, and AQP5 enhance the motility and invasiveness of pancreatic cancer by facilitating actin cytoskeleton remodeling, enabling cancer cells to migrate efficiently through tissue barriers." (PMID 40305202, 2025). "The strong association found between AQP5 and EGFR, and the associations between AQP3/AQP9 and c-Jun in pancreatic tumor tissues highlight the implications of AQPs in the settings of tumorigenesis." (PMID 40305202, 2025). "Previously, we have characterized the implication of AQP3 and AQP5 in ROS accumulation, cell adhesion, proliferation, and motility in human pancreatic cancer BxPC3 cells, further supporting their involvement in pancreatic cancer progression." (PMID 40305202, 2025). "Recently, we reported the modulation of the most cancer-associated AQPs—AQP1, AQP3, AQP5, and AQP9—in paired pancreatic tumors and adjacent healthy tissues from a pancreatic cancer cohort." (PMID 40305202, 2025). "In pancreatic tumor tissues, AQP5 was correlated with EGFR, and AQP3 and AQP9 were correlated with c-Jun." (PMID 40305202, 2025). "Altogether, our results highlight the potential role of AQP3 and AQP5 as prognostic biomarkers in pancreatic cancer." (PMID 40305202, 2025). "The observed correlations further support the role of AQP3 and AQP5 in pancreatic cancer progression and reinforce the clinical relevance of targeting AQPs in future therapeutic strategies." (PMID 40305202, 2025). "Human AQP5 was shown to be a highly efficient peroxiporin, characterized in transformed yeast cells exposed to oxidative stress, and in human pancreatic cancer cells." (PMID 38451099, 2024). "Then, the impact of silencing AQP3 and/or AQP5 in biophysical, biomechanical, and morphological properties of pancreatic cancer cells was investigated by atomic force microscopy (AFM) and two-photon microscopy (TPM)." (PMID 35455986, 2022). "Taken together, our findings demonstrate that the expression of AQP3 and AQP5 promotes alterations of the biological and biomechanical properties of these pancreatic cancer cells." (PMID 35455986, 2022). "Other markers, such as AQP5, CDC25C, and TMEM170B, have been proved to be associated with the prognosis of pancreatic cancer." (PMID 35898870, 2022). "In this context, we show, for the first time, that AQP5 contributes to membrane ordering in pancreatic cancer cells, rendering the membrane less fluid and possibly more prone to chemotherapy resistance." (PMID 35455986, 2022). "The results indicated that AQP5 mRNA expression was very high in most tumors, such as adrenocortical carcinoma, pancreatic carcinoma, cholangiocarcinoma, and colon adenocarcinoma, compared to the corresponding normal tissues." (PMID 35619903, 2022). "Contrary to expected, AQP5 was positively correlated with CDH1 in pancreatic tumor tissues." (PMID 40305202, 2025). "In addition, AQP5 overexpression in pancreatic cancer cells was found to promote cancer cell migration due to its peroxiporin activity." (PMID 39941100, 2025). "Recently, we assessed the expression of tumor-associated AQPs (AQP1, AQP3, AQP5, and AQP9) in the same pancreatic cancer cohort, revealing AQP1 downregulation in tumor tissues, and AQP3 upregulation in low-invasiveness grade tumors compared to high invasiveness grade pancreatic tumors." (PMID 40305202, 2025). "Further validation may establish AQP3 and AQP5 as additional prognostic biomarkers for pancreatic cancer, potentially contributing to improving early disease detection, prognosis, and personalized treatment strategies." (PMID 40305202, 2025).